RGMB-AS1 (RGMB antisense RNA 1)
Gene: Long non-coding RNA gene on chromosome 5 (98,769,618 to 98,774,507, reverse strand). Ensembl gene ENSG00000246763.
Diseases named in the same sentence as RGMB-AS1 in open-access papers:
RGMB-AS1 is named in the same sentence as 3 diseases in open-access papers, as found by Europe PMC text mining. Sharing a sentence is not in itself a finding about the gene and the disease. The quoted sentences say what the papers report.
cancer (1 paper, 2022). A tumor composed of atypical neoplastic, often pleomorphic cells that invade other tissues. "It is worth noting that, as a tumor suppressor or oncogenic molecule, LncRNA RGMB antisense RNA 1 (RGMB-AS1) refers to the regulation of malignant tumors during the progression of many cancers." (PMID 35184697, 2022).
tumor (1 paper, 2022). "Another correlation with nodal metastases was identified for RGMB antisense RNA 1 (RGMB-AS1), whose high expression in LSCC tissues has been associated with advanced tumor stage and poor prognosis, as well." (PMID 35406495, 2022).
RGMB-AS1 also shares sentences with these, for which no sentence is quoted: prostate carcinoma (1 paper).